GFAP (glial fibrillary acidic protein)
Diseases named in the same sentence as GFAP in open-access papers (continued):
Sharing a sentence is not in itself a finding about the gene and the disease.
brain injury (continued). "Plasma glial fibrillary acidic protein concentration was significantly increased 1-h post-injury in mild traumatic brain injury cases compared to the non-injured group (P = 0.017)." (PMID 33543129, 2020). "Following experimental and clinical traumatic brain injury, UCH-L1 and GFAP concentrations increase in biological fluids in the superacute (UCH-L1) and acute (UCH-L1, GFAP) phase and then, depending on injury severity, they normalize over 3–4 days unless secondary events occur." (PMID 32588294, 2020). "Although promising, at the present time there is not enough evidence to suggest that GFAP can be used clinically as a reliable discriminant of CT-positive and CT-negative brain injury." (PMID 29255443, 2017). "For instance, attenuation of reactive gliosis through genetic deletion of intermediate filaments (IFs) glial fibrillary acidic protein (GFAP) and vimentin in animals subjected to traumatic brain injury improved regeneration, with a positive effect on complete synaptic restoration." (PMID 23118728, 2012). "No concentration peak for GFAP was found, but the boxer with the reported concussion had among the highest concentration levels of GFAP one day after the bout and the levels had decreased from 960 to 500 ng/L at follow up, 15 days after the bout." (PMID 22496755, 2012). "Brain astrocytes do not show major losses in GS even while upregulating glial fibrillary acidic protein (GFAP) in brain trauma." (PMID 18483561, 2008). "GFAP levels are elevated in athletes with sports-related concussion, and those with loss of consciousness (LOC) or posttraumatic amnesia (PTA) have significantly higher levels than athletes with concussion but neither LOC or PTA." (PMID 35717463, 2022). "The overall pattern of GFAP immunoreactivity in the hippocampus suggested that the very high-fat diet (HF60), but not the HF45 diet, slightly promoted (p = 0.1) astrocyte hyperplasia, which is indicative of gliosis, a common response occurring in many types of brain injuries." (PMID 29566703, 2018). "While the presence of GFAP in blood following traumatic brain injury (TBI) is thought to occur via the recently identified glymphatic pathway, it is not entirely clear whether serum GFAP in these studies is soluble or exosome-associated." (PMID 29383115, 2017). "It has been shown that patients who have suffered multiple traumatic injuries, with no history of brain injury, show control levels of GFAP expression, while patients with a history of brain injury show increased GFAP expression as a function of the severity of brain injury." (PMID 23248582, 2012). "In conclusion, this study shows that the repetitive head trauma occurring in olympic boxing may induce changes in CSF NFL, GFAP, T-tau and S-100B, even without anamnestic or clinical symptoms of a concussion or traumatic brain injury." (PMID 22496755, 2012). "Likewise, knocking down VIM expression using antisense complementary DNA for VIM or preventing hypertrophy of astrocytic processes in GFAP-/-VIM-/-double knockout mice can reduce glial scarring and improve neuronal regeneration and recovery after traumatic brain injuries." (PMID 22146123, 2011). "Therefore, the significant decrease in GFAP+ and VIM+ astroglia after anesthetic exposure as observed in this study may offer an alternative explanation of neuroprotection seen in other experimental studies of brain injuries involving the use of isoflurane anesthesia." (PMID 22146123, 2011). "GFAP was believed to occur in non-myelinating Schwann cells in the peripheral nervous system (PNS), and the enteric glial cells in the enteric nervous system (ENS), which might be a suitable measure for patients with brain injury." (PMID 34054412, 2021).
astrocytoma (118 papers, 2002 to 2025). "In this cohort, patients presented with the less common type II RESLES, possibly a pathological change secondary to GFAP astrocytoma and associated viral infection." (PMID 39720731, 2024). "Since the first published article of GFAP’s associations with astrocytoma in 1972, there have been dozens of studies about how this protein interfaces with astrocytoma." (PMID 33227903, 2020). "Using the same antibody to pSer13-GFAP that we used in this paper (clone KT13) it was later shown that Aurora-B and Rho-associated kinase phosphorylate GFAP in cultured astrocytoma cells during mitosis." (PMID 31682229, 2019). "A loss of GFAP - the typical astrocyte IF protein - in higher grade astrocytomas was described more than 40 years ago, and astrocytoma type IV has been characterized into subtypes on the basis of IF expression." (PMID 29152145, 2017). "Several GFAP splice variants have been identified and the main variants expressed in human astrocytoma are the GFAPα and GFAPδ isoforms." (PMID 29152145, 2017). "In order to gain new insights into astrocytoma biology, we studied GFAP-isoform expression in resected astrocytoma from patients (TCGA database) as well as the downstream transcriptional changes in astrocytoma cells caused by modulation of these GFAP-isoforms." (PMID 29152145, 2017). "Exome-NGS revealed a mutation in a previously neglected GFAP isoform, GFAP-ε, which disrupts the GFAP-associated filamentous cytoskeletal meshwork of astrocytoma cells." (PMID 23634874, 2013). "Loss of GFAP expression is frequently observed in high-grade astrocytoma." (PMID 32456305, 2020). "The loss of GFAP expression, frequently observed in high-grade astrocytoma, may represent the undifferentiated state of these cells." (PMID 27471070, 2016). "Both Olig2 and GFAP can be expressed in astrocytomas and oligodendrogliomas, whereas vimentin is more strongly expressed in astrocytomas." (PMID 40362055, 2025). "While GFAP, a marker highly expressed in astrocytomas, showed minimal expression in highly proliferative GFP+ cells, it does not correlate directly with malignancy grade, as different GFAP isoforms can coexist in these tumors." (PMID 40917877, 2025). "GFAP is key intermediate filament protein in astrocytes, used as a marker for gliomas and astrocytomas." (PMID 40575267, 2025). "Conversely, Olig2-CKO tumors are highly diffuse “astrocytomas” dominated by high levels of GFAP, which overlaps extensively with tdTOM." (PMID 39609428, 2024). "Histopathological features were of a moderately hypercellular astrocytoma (GFAP, Olig2 immunohistochemical staining positive) with mild cytological atypia and focal infiltrative growth (demonstrated with neurofilament NF68 staining)." (PMID 39427038, 2024). "We previously found that high plasma GFAP was associated with GBM, low GFAP and high FABP4 were associated with meningiomas and low GFAP and low FABP4 were associated with astrocytomas." (PMID 38879494, 2024). "High plasma GFAP concentration was associated with GBM, low GFAP and high FABP4 were associated with meningiomas, and low GFAP and low FABP4 were associated with astrocytomas and oligodendrogliomas." (PMID 38879494, 2024). "Control LN-18shSCR cells treated with iTGFβRI exhibited elevated expression of specific astrocytoma markers such as GFAP and Snail." (PMID 38672477, 2024). "Most of the rat brain tumors have minimal expression of glial fibrillary acidic protein (GFAP) although the morphology is comparable to that of human astrocytomas." (PMID 38232086, 2024). "GFAP can also be detected in tumors (e.g., myoepithelial tumors of soft tissue, salivary gland tumors and astrocytomas)." (PMID 39272777, 2024).
astrocytoma (continued). "iPSC lines were first differentiated to forebrain-patterned SOX2+/NESTIN+/SOX10− neural progenitor cells (NPCs) and then to GFAP+ astrocytes, the cell-of-origin of astrocytoma, using a modified astrocyte differentiation protocol." (PMID 36973285, 2023). "Based on previous research, high-grade astrocytoma exhibits much lower levels of GFAP expression than low-grade astrocytoma." (PMID 37090987, 2023). "Immunohistochemical analysis revealed strong GFAP expression among CT-2A cells which corresponds to the high GFAP expression seen in human astrocytomas." (PMID 37366911, 2023). "In clinical practice, GFAP is commonly used as a classical marker of astrocytoma to confirm glial differentiation." (PMID 35885538, 2022). "With the objective to accurately distinguish the differentiation state of astrocytomas, it will be necessary to assess the predominant GFAP isoform expression, either GFAPα or GFAPδ." (PMID 35372061, 2022). "GFAP positive cells are present in tumours of all malignancy grades with a tendency for decreased GFAP levels with increasing astrocytoma grade." (PMID 35919979, 2022). "GFAP is expressed not only in normal brain tissue, but also in brain tumors like astrocytoma, where it is one of the most important markers for astrocyte lineage." (PMID 35372061, 2022). "Although the GFAP serum concentrations of most astrocytomas are far below this limit, some astrocytomas exceed this limit with GFAP levels of up to 2.04 ng ml−1." (PMID 35919979, 2022). "We observed that most cells are GFAP+ astrocytoma cells, as well as relatively low proportions of PTRPC+ immune cells and MOG+ oligodendrocytes in this tumor." (PMID 34805184, 2021). "Contralateral normal cortex from astrocytoma-bearing dogs demonstrated a homogeneous distribution of Iba-1+ cells with long, branched processes, interspersed between a homogeneous population of GFAP+ cells." (PMID 34131649, 2021). "In our series, we found that plasma GFAP had a sensitivity of 18.2%, 35.3% and 57.5% for astrocytoma (N = 11), oligodendroglioma (N = 17) and GBM (N = 40), respectively." (PMID 33501422, 2021). "CLSM of cell cultures isolated from GBMs and astrocytomas revealed GFAP+ tumor cells and CD117+ cells featuring Tc morphology." (PMID 32064038, 2020). "GBM and astrocytoma originate from astroglial cells, and the number of cells expressing GFAP is inversely proportional to the extent of anaplasia." (PMID 32456305, 2020). "Diffuse astrocytomas (comparison group) also expressed GFAP; their Ki-67 index was from 1.4 to 4, with 2.96 ± 0.30% on average." (PMID 32064038, 2020). "Treatment of 1321N1 astrocytoma cells with exogenous WT α-syn led to a statistically significant (p, 0.05) increase in GFAP immunofluorescence and α-syn aggregates were observed at the cell periphery (arrows)." (PMID 32911644, 2020). "In some neurodegenerative diseases as well as in the astrocytoma of grade IV, GFAP isoforms with lower molecular weight were better expressed when compared to the control condition." (PMID 32982688, 2020). "IDH1R132H- or EGFRvIII-dependent inhibition of differentiation makes more sense if classical NSC or GFAP + NP would be the origin of GB (question mark next to astrocytoma)." (PMID 32774372, 2020). "GFAP is better characterized as a potential astrocytoma biomarker than the previously discussed proteins." (PMID 33227903, 2020). "Immunolabeling for glial fibrillary acidic protein (GFAP) is considered supportive of the diagnosis of astrocytoma whereas immunolabeling for CNPase is considered supportive of the diagnosis of oligodendroglioma." (PMID 31788444, 2019). "According to the literature, with the increase of the malignant degree of astrocytoma, the production of GFAP decreased." (PMID 30285781, 2018). "Together, our data and previous observations suggest that GFAP-isoforms in astrocytoma regulate the malignant phenotype of cells both by regulating their growth as well as their invasive capacity." (PMID 29152145, 2017).
astrocytoma (continued). "Our data imply that regulating GFAP expression and splicing are novel therapeutic targets that need to be considered as a treatment for astrocytoma." (PMID 29152145, 2017). "These include astrocytomas of varying grades resulting from glial fibrillary acidic protein (GFAP)-regulated expression of v-src." (PMID 29052807, 2017). "Nevertheless, we here provide evidence for an important role of GFAP-isoforms in astrocytoma malignancy that will direct future research." (PMID 29152145, 2017). "Although the overall implications of these findings remain to be elucidated, studies in a human astrocytoma cell line indicate that reduced GFAP expression affects astrocyte maturation and their ability to respond to neurons." (PMID 28993428, 2017). "We first analysed GFAP-isoform expression in a large RNA sequencing dataset from TCGA and observed different levels of GFAPα expression in astrocytomas of different grade as well as a different GFAPδ/α ratio." (PMID 29152145, 2017). "To identify those GFAP-isoform induced transcriptomic changes that are relevant for astrocytoma malignancy, we compared our in vitro transcriptomic data to the TCGA derived patient transcriptomic data." (PMID 29152145, 2017). "Since wild-type EGFR and mutant EGFRvIII are the most common gain-of-function alterations in malignant human astrocytomas, they reported the generation of mice expressing these proteins under the regulation of the GFAP promoter." (PMID 29052807, 2017). "GFAP is the signature IF of astrocytoma cells, nevertheless the function of GFAP in astrocytoma biology is still unclear." (PMID 29152145, 2017). "To further investigate the regulation of these genes of interest by GFAP, we calculated the strength of correlation to GFAPα and the GFAPδ/α ratio within astrocytoma grade." (PMID 29152145, 2017). "The majority of the astrocytomas express the intermediate filament protein Glial Fibrillary Acidic Protein (GFAP)." (PMID 29152145, 2017). "This reduces the influence of astrocytoma grades on the correlation of GFAP with expression levels of a gene." (PMID 29152145, 2017). "The relationship between GFAP-isoforms and astrocytoma malignancy that we show here is based on a correlation." (PMID 29152145, 2017). "The genes that emerged from this final analysis are the genes we consider most likely to be regulated by a change in GFAP-isoforms in astrocytoma." (PMID 29152145, 2017). "HDAC inhibition also mediates decreases in Glial fibrillary acidic protein (GFAP) expression in primary human astrocytes and in astrocytoma cells." (PMID 28492482, 2017). "Astrocytoma cells react strongly with GFAP and negatively with synaptophysin, neurofilament, desmin, cytokeratin, and epithelial membrane antibodies." (PMID 27568373, 2016). "We investigated the IF network morphology by immunostainings for GFAP, and we observed that the different GFAP isoforms gave similar results in both the primary human astrocytes and the human U251 astrocytoma cells." (PMID 27141937, 2016). "Astrocytes and astrocytoma cells tightly regulate the expression of at least 10 different GFAP isoforms." (PMID 27141937, 2016). "Anaplastic astrocytoma cells expressed high levels of GFAP, while nestin expression was detected only in scattered cells." (PMID 25710480, 2015). "C6 cells transfected with GFAP cDNA showed significantly reduced tumor growth while anti-sense GFAP-transfected astrocytoma cells showed increased invasiveness and growth." (PMID 24205314, 2013). "Transient transfection of N-GFAP into a human astrocytoma cell line induces the formation of cytoplasmic aggregates, which also disrupt the endogenous GFAP networks." (PMID 24102621, 2013). "GBM is a form of a high-grade astrocytoma, with a large proportion of the tumour expressing the astrocyte marker, glial fibrillary acidic protein (GFAP)." (PMID 22771539, 2013).
astrocytoma (continued). "Some examples are: 1) Expression of a constitutively activated tyrosine kinase v-src in GFAP-expressing cells was shown to induce astrocytomas with a less than 20% penetrance." (PMID 22348397, 2012). "The growth and invasive potential of the antisense GFAP-transfected astrocytoma cells was significantly enhanced." (PMID 20007262, 2011). "All tumors generated were composed of regions with more oligo- and mixed astrocytoma histologies, with areas that were highly positive for GFAP and others positive for Olig2." (PMID 21931722, 2011). "The astrocyte marker, GFAP, is involved as a collaborator in the complex cellular processes controlling astrocytoma cell morphology, differentiation and proliferation." (PMID 20007262, 2011). "V12Ha-Ras transgenic mice under the control of the GFAP promoter form astrocytomas that have the added genetic complexity of the aberrant expression of p16, p19, and PTEN while overexpressing EGFR, MDM2, and CDK4, with chromosomal rearrangements comparable to human astrocytomas." (PMID 41154198, 2025). "Likewise, a gradual decline in GFAP production was reported as the malignancy of astrocytoma cells increases." (PMID 39821858, 2025). "Similarly, GFAP had been recommended as a prognostic marker in distinctive cancers, such as malignant astrocytoma." (PMID 38440732, 2024). "GFAP is an intermediate filament protein found in astrocytes within the CNS, and positive staining has long been established in CNS pathologies, including astrocytomas and gliomas." (PMID 39582680, 2024). "The gene GFAP is a classical marker of astrocytoma and is exclusively expressed in brain tissue." (PMID 39118043, 2024). "Astrocytomas and oligodendrogliomas were characterized by their typical histological features and, when required, further classified based on immunoreactivity against GFAP and Olig2 on >50% of neoplastic cells, respectively." (PMID 39061577, 2024). "Interestingly, in a mouse model of brain tumors, GFAP-positive intercellular astrocytoma membrane tubes with a width of over 1 μm and a length of more than 100 μm, called “tumor microtubes” (TMs), were found." (PMID 37886397, 2023). "Prospective studies have investigated using GFAP as a blood-based biomarker for astrocytomas." (PMID 35919979, 2022). "It has been shown previously that GFAP expression is influenced by astrocytoma grade." (PMID 35919979, 2022). "In contrast, transient receptor potential (TRP) induced mutations in astrocyte glial fibrillary acidic protein (GFAP) and glutamate aspartate transporter (GLAST) showed significant low-grade astrocytoma formation with differences in growth and progression kinetics." (PMID 35057010, 2022). "Besides, the immunohistochemical staining results revealed that this tumor shows strong expression of the GFAP, a classic marker of astrocytoma." (PMID 34805184, 2021). "We analyzed images of paraffin-embedded canine astrocytoma tumor samples (grades II–IV) and normal canine cortex utilizing the microglia/macrophage marker, ionized calcium-binding adapter molecule (Iba-1) and astrocyte marker, GFAP." (PMID 34131649, 2021). "As the majority of astrocytomas are preferentially located in areas rich in neural progenitor cells, the tumour-initiating capacity of astrocytes has been difficult to assess, as they co-express markers of neural precursor cells (e.g. GFAP)." (PMID 29759978, 2018). "GFAP-positive expression could be found in astrocytoma, ventricular duct tumor, mixed glioma of the astrocytes line, giant cell astrocytoma, pleomorphic yellow astrocytoma, astrocytoma, glioma sarcoma, and so on." (PMID 30285781, 2018).